RET (ret proto-oncogene)
Diseases named in the same sentence as RET in open-access papers (continued):
Sharing a sentence is not in itself a finding about the gene and the disease.
Hirschsprung disease (continued). "The moderate frequency of the Hirschsprung disease-associated minor allele of RET g.9349G>A in the Indian cohort is in contrast with the relatively low frequency of the disease in India (2.8 per 10,000 births)." (PMID 18248681, 2008). "As an example, a common noncoding variant in a RET enhancer has recently been shown to be a strong risk allele for Hirschsprung disease, explaining the paucity of coding mutations found in families showing linkage to the RET locus." (PMID 17437132, 2007). "A highly significant association of RET polymorphisms, specifically the variant A45A, with Hirschsprung disease has also been observed." (PMID 12085189, 2002). "The importance of RET signaling in nervous system development was proven since mutations in this receptor can cause Hirschsprung’s disease, a rare intestinal motility disorder characterized by aganglionic megacolon." (PMID 41562905, 2025). "Isolated Hirschsprung disease is most frequently caused by LoF RET variants." (PMID 40138217, 2025). "Mutations in the receptor tyrosine kinase RET have been identified in approximately 50% of familial cases of Hirschsprung disease but the cellular processes misregulated in this condition remain unclear." (PMID 35694443, 2022). "In a boy with Hirschsprung disease, a homozygous missense variant in RET was identified." (PMID 34497401, 2021). "Among the 4 different RET mutants identified in colon cancer patients we excluded the P270L variant because it represented less than 10% of the cell population and the R77C since it has been observed in a case of Hirschsprung’s disease." (PMID 29665843, 2018). "On the other hand, a loss of function mutation of RET leads to Hirschsprung’s disease." (PMID 27409604, 2016). "Close interactions between the enteric nervous and vascular systems are indicated in vitro in cell culture assay of vascular cells and ENS-derived cells, in vivo in tyrosine kinase receptor RET knockout enteric ganglia deficiency mice and in human Hirschsprung’s disease." (PMID 27163330, 2016). "Dysregulated RET signalling is associated with disease: inactivating mutations of RET lead to a form of neurocristopathy called Hirschsprung’s disease, whereas mutations of RET resulting in constitutively active isoforms are associated with several forms of inherited and somatic cancers." (PMID 27841748, 2016). "Mutations of RET and GDNFgenes may be involved in Hirschsprung's disease, which is characterized by theabsence of intramural ganglion cells in the hindgut, often resulting in intestinalobstruction." (PMID 26650444, 2015). "Thus, the penetrance of RET gene mutations in Hirschsprung disease depends not only on the nature of the mutation but also on the allele dosage." (PMID 23820649, 2013). "For example, a non-coding single nucleotide polymorphism (RET+3) within a conserved enhancer element in the first intron of RET, a receptor tyrosin kinase, has been reported to be significantly associated with Hirschsprung disease featured by congenital aganglionosis with megacolon." (PMID 19570198, 2009). "Hirschsprung disease (HSCR) a common developmental disorder of the enteric nervous system is caused due to genetic dysregulation of multiple genes primary among them RET, which contain multiple disease associated enhancer variants." (PMID 37948459, 2023). "Hirschsprung disease (HSCR) is associated with deficiency of the receptor tyrosine kinase RET, resulting in loss of cells of the enteric nervous system (ENS) during fetal gut development." (PMID 37948459, 2023). "There are numerous published studies on the association between RET polymorphisms and susceptibility to Hirschsprung disease (HSCR)." (PMID 36324815, 2022). "Loss-of-function mutations of RET have been shown to be associated with Hirschsprung disease and Down's syndrome (HSCR-DS) in humans." (PMID 33561442, 2021).
Hirschsprung disease (continued). "Interestingly, contradictory data exists from mouse models and patients with enteric ganglia deficiency: with a reduction of blood vessel density in the RET knockout mouse model, but more blood vessels detected in the enteric aganglionic zone of patients with Hirschsprung’s disease." (PMID 27163330, 2016). "The idea answer is: Coding sequence mutations in RET, GDNF, EDNRB, EDN3, and SOX10 are involved in the development of Hirschsprung disease." (PMID 40766492, 2025). "Familial Hirschsprung disease (F-HSCR) is often associated with variants in the RET proto-oncogene." (PMID 40656247, 2025). "AC had been diagnosed with Hirschsprung’s disease after birth and was found to carry a pathogenic RET variant consistent with MEN2A." (PMID 39555152, 2025). "RET and GFRα-1 are the responsible genes for Hirschsprung disease, from which severe cases of IGD suffer." (PMID 38225934, 2024). "Familial and isolated forms of Hirschsprung disease have been associated with various genetic factors, although mutations in the EDNRB and RET proto-oncogenes are commonly reported." (PMID 38883048, 2024). "RET, NRG1, and L1CAM genes are reported as pathological gene variants associated with the incidence of different variants of Hirschsprung's disease." (PMID 38169757, 2023). "Inactivating RET mutations are associated with ENS diseases, e.g., Hirschsprung Disease, in which distal bowel lacks ENS cells." (PMID 36555308, 2022). "In this project, we performed an exploratory analysis to look for statistical epistasis in two Hirschsprung disease related regions of the genome—the TADs encompassing the RET and NRG1 genes." (PMID 36443333, 2022). "In a proof of principle example, RUNNER successfully recaptured (P< 2.5E-6) the known causal gene RET, and prioritized another known gene EDNRB of Hirschsprung disease." (PMID 34931221, 2022). "Developmental studies in model organisms and genetic studies of Hirschsprung's disease have provided a detailed understanding of enteric nervous system development via expression of the RET gene." (PMID 35434281, 2022). "The RET gene was originally described as a human oncogene, but it was later established that RET plays a crucial role in the development of enteric neurons and defects in the human RET gene result in the syndrome known as Hirschsprung's disease." (PMID 35434281, 2022). "In addition, compared with previous findings regarding the 4 RET variants (rs2506030, rs7069590, rs2505998 and rs2435357), our present results have shown that the odds ratios have the same magnitudes, suggesting that the cases studied here are representative of Hirschsprung disease." (PMID 32139661, 2020). "According to our detailed evaluation, she suffered from Hirschsprung disease (HD), growth retardation, medullary thyroid carcinoma (MTC) and mucosal neuroma due to a mutation in the RET gene." (PMID 32600305, 2020). "The effect of modifier genes, such as RET in Hirschsprung disease as well as the possible role of environmental factors have been proposed to explain clinical heterogeneity." (PMID 33047879, 2020). "Since Ednrb(−/−); RET‐mice congenitally develop white hairs and die from Hirschsprung disease within one month, Ednrb(+/−); RET‐mice were used in this study." (PMID 33159498, 2020). "Taken together, our present data show that genetic variants and haplotypes in RET, ARHGEF3 and CTNNAL1 confer an altered risk to Hirschsprung disease in the Han Chinese population." (PMID 32139661, 2020). "NRTN mutations have been associated with Hirschsprung’s disease, implicating that the NRTN-induced signaling of RET plays a role in the growth or guidance of enteric ganglia." (PMID 31535977, 2019). "The multiplex MLPA-based strategy presented in this study was originally developed to detect germline copy number variation (CNV) of 4 genes related to Hirschsprung disease, including the RET gene (exons 1–21)." (PMID 31288802, 2019).
Hirschsprung disease (continued). "Collectively, the results imply that mutation in GDNF, NRTN or RET reduce the affinity for GFRA1 interaction, resulting in Hirschsprung’s disease." (PMID 29617307, 2018). "The concomitant occurrence of Hirschsprung's disease and MEN 2 is a relatively rare event, due to the presence of a “Janus” variant in the RET proto-oncogene: these variants can act both as a gain-of-function and a loss-of-function variant." (PMID 30072953, 2018). "RET malfunction can also lead to congenital abnormalities characterized by failure of neuroblast migration and defective maturation of the enteric nervous system (Hirschsprung disease), a condition that in some families coexisted with MEN2A." (PMID 28634440, 2017). "SRY effects on MAOA and RET expression could affect normal synaptogenesis and neurotransmission, and enteric nervous system development, and contribute to pathogeneses of diseases associated with these two genes, i.e. depression/cognitive disorders and Hirschsprung disease respectively." (PMID 28646221, 2017). "RET is downstream ASCL1 (another candidate for Hirschsprung disease) in noradrenergic brain stem neurons important for respiratory rhythm modulation." (PMID 27621700, 2016). "Early studies targeting specific genomic loci by extensive long-range mapping have established a handful of enhancers as causative in very specific disorders such as the beta-globin enhancers in Thalassemia’s and a RET enhancer in Hirschsprung disease." (PMID 27628759, 2016). "The role of TTF-1 in the development of Hirschsprung’s disease by RET interaction has been recently outlined." (PMID 27409604, 2016). "It was recently shown that TTF-1 is also involved in the transcription of human RET in Hirschsprung’s disease." (PMID 27409604, 2016). "Some families with Hirschsprung disease and Bardet–Biedl syndrome harbour mutations in their BBS4, BBS5, BBS7 and RET genes." (PMID 23820649, 2013). "It appears that RET, the major gene involved in the aetiology of Hirschsprung disease, acts as a modifier of the Hirschsprung disease phenotype in Bardet–Biedl syndrome." (PMID 23820649, 2013). "A 32-year-old lady (CE) with neonatal history of Hirschsprung’s disease was referred for genetic screening following RET oncogene mutation diagnosis in her mother, a mutation that was confirmed for CE, in keeping with a diagnosis of MEN2A." (PMID 39555152, 2025). "Hirschsprung’s disease caused by LoF variants in RET was not the focus of this study; however, we report three novel variants interpreted as del-VUSs: NC_000010.11:g.43128194A>T, NC_000010.11:g.43128118C>A, and NC_000010.11:g.43128131A>G." (PMID 39301547, 2024). "Abnormalities of the RET gene result in Hirschsprung's disease." (PMID 35434281, 2022). "Although palatal and retinal anomalies in the context of chromosomopathies and some mono−/oligogenic syndromes are reported associated with Hirschsprung disease the role of inactivating RET mutations in these cases is not clarified." (PMID 32948239, 2020). "They declared that it is difficult to predict tumor risk for patients with familial or sporadic Hirschsprung disease and that in combined MEN2A/Hirschsprung disease families RET gene testing, tumor screening, and prophylactic thyroidectomy are indicated as in MEN2A." (PMID 32103327, 2020). "It has recently been demonstrated that the interaction between RET and PHOX2B polymorphisms substantially affects the risk of Hirschsprung disease, suggesting that HSCR, as a multifactorial genetic disorder, requires the interactions of multiple unlinked genes to produce the phenotype." (PMID 32139661, 2020). "RET is an essential tyrosine kinase receptor for generation of the enteric nervous system; deficiency of RET led to an absence of enteric ganglia and subsequent development of Hirschsprung's disease." (PMID 31275305, 2019).
Hirschsprung disease (continued). "Dysregulation of RET signaling is linked to many human diseases, such as Hirschsprung's disease, a disorder characterized by lack of enteric ganglia in parts of the intestine, and multiple endocrine neoplasia type 2 (MEN 2A and 2B) (Ibáñez, 2013)." (PMID 31535977, 2019). "Mutations in RET are common in Hirschsprung’s disease which is characterized by the absence of neuronal ganglia in various parts of the colon, leading to severe constipation and intestinal obstruction during childhood." (PMID 29617307, 2018). "The RET proto-oncogene was identified as a major locus involved in Hirschsprung disease (HSCR)." (PMID 28256518, 2017). "RET mutations, which cause multiple endocrine neoplasia (MEN) syndrome and Hirschsprung disease, were also described in bilateral renal hypodysplasia/agenesis cases and, in addition, patients with Hirschprung disease are described to carry urinary tract defects." (PMID 28398236, 2017). "This strongly supports our hypothesis that miRNA profiling can identify dysregulation of RET and RET-regulating pathways in Hirschsprung’s disease." (PMID 26933947, 2016). "The same SNP is known to be associated with Hirschsprung disease (HSCR) through a similar mechanism: lack of adequate levels of RET expression during development does predispose to impaired enteric nervous system and therefore to colonic aganglionosis." (PMID 27034161, 2016). "Additionally, if EDNRB is heterozygously deleted in a mouse transgenically expressing RET—another Hirschsprung disease gene—mice develop de novo melanoma lesions." (PMID 25679399, 2015). "Additionally, some rare cases have also been reported to be associated with specific RET mutations in many MEN 2 families, such as cutaneous lichen amyloidosis (CLA), Hirschsprung's disease (HSCR), and corneal nerve thickening (CNT)." (PMID 26356818, 2015). "Loss-of-function mutations of the RET proto-oncogene results in Hirschsprung disease, a genetic disorder characterized by congenital absence of enteric neurons in the gastrointestinal tract." (PMID 25330015, 2014). "On the other hand, joint gene-gene effects (e.g. RET and PHOX2B; RET and HOX genes) may also have a substantial impact on the risk of Hirschsprung disease." (PMID 24073265, 2013). "Common variants in RET and NRG1 have been associated with Hirschsprung disease (HSCR), a congenital disorder characterised by incomplete innervation of distal gut, in East Asian (EA) populations." (PMID 36443333, 2022). "Hirschsprung disease, the most important congenital colonic dysmotility in children results from neural crest migration, differentiation, proliferation, or apoptosis defects where the rearranged during transfection (RET)-Protooncogene pathway has a central role." (PMID 32948239, 2020). "However, we have identified other two families with non-cysteine RET mutations, (K821E and Y791F) with one single member with Hirschsprung’s disease and, so far, no one with MTC." (PMID 31510104, 2019). "Hence, a dysregulation of RET expression by HOXB5 could result in insufficient RET expression and Hirschsprung disease." (PMID 31519213, 2019). "In this national study of the largest RET C611Y cohort to date, we provided a detailed description of disease manifestations (MTC, PHEO, PHPT, CLA, and Hirschsprung’s disease) and survival." (PMID 39941743, 2025). "Thus, RET regulated Ca2+ signaling may be involved in Hirschsprung's disease and MEN2a/b." (PMID 22355350, 2012). "PHOX2B appears to influence the development of Hirschsprung’s disease through interactions with the RET promoter, although not directly; according to studies, there is no physical binding between them." (PMID 34949014, 2021). "Our results appear to indicate that CNVs in the coding region of RET and the other 3 HSCR related genes here tested are not a common molecular cause of Hirschsprung disease, at least in the Spanish population." (PMID 19925665, 2009).
Hirschsprung disease (continued). "The RET gene encoding a tyrosine-kinase receptor, plays a crucial role in the development of ENS, and mutations in this gene are associated with Hirschsprung disease (HSCR), a congenital disorder characterized by the absence of enteric ganglia in distal colorectum, leading to functional obstruction." (PMID 39301033, 2024).
breast carcinoma (121 papers, 2002 to 2025). "According to the extant data, RET overexpression occurs in 40–60% of breast tumors and it is reported to be more common than RET rearrangements or mutations in breast cancer." (PMID 41373459, 2025). "This review aims to recapitulate the existing evidence about the role of RET oncogene in breast cancer, from its pathogenic and potentially prognostic role, to the clinical applications of RET inhibitors." (PMID 39211557, 2024). "Although RET has been associated with ER+ breast cancer tumorigenesis and endocrine treatment response, the role of RET in resistance mechanisms to combined fulvestrant and CDK4/6i has not been evaluated." (PMID 39931212, 2024). "A missense variant, (NM_020975.6):c.2410G>A, p.(Val804Met) in RET proto-oncogene, was identified in a female patient diagnosed with breast cancer at the age of 52." (PMID 39684258, 2024). "High expression of the receptor tyrosine kinase REarranged during Transfection (RET) has been associated with resistance to endocrine therapy in breast cancer, but the role of RET in CDK4/6i treatment response/resistance remains unexplored." (PMID 39931212, 2024). "Surprisingly, in our series,we reported acquired RET mutations in 11% of “neo RAS wt”.RET point mutations have been described in different cancers, such as breast cancer,colorectal adenocarcinoma and gastrointestinal stromal tumors." (PMID 37064137, 2023). "RET and GFRα1 are implicated in promoting breast cancer-cell survival, proliferation and migration and in vitro data support the involvement of RET signaling pathways in development of drug resistance." (PMID 33233403, 2020). "A consecutive TMA study of 245 primary human breast cancers showed an association between RET expression and recurrent disease after adjuvant Tamoxifen treatment." (PMID 30621641, 2019). "Here we report RET gene alterations, including amplification, missense mutations, known fusions, novel fusions, and rearrangements in breast cancer." (PMID 30446652, 2018). "In many cases, RET gain-of-function is associated with breast cancer formation through enhanced cell proliferation, migration and cell scattering, as well as, through enhanced cytokine production." (PMID 27769065, 2016). "Elevated RET expression has been associated with the development of endocrine resistance in human breast cancer." (PMID 25409876, 2014). "In addition to its involvement in the initiation and progression of breast cancer, studies found that RET was associated with resistance to endocrine therapy." (PMID 38738791, 2024). "While there has been minimal research on RET’s function in ER-negative breast cancer to date, this finding suggests that activating RET mutations may warrant further study in this specific subtype of breast cancers." (PMID 36918928, 2023). "On the one hand, GFRα1 was identified as a target protein of ST3 beta-galactoside alpha-2,3-sialyltransferase 1 (ST3GAL1), which regulates the GDNF/GFRα1/RET pathway in breast cancer cells by mediating O-linked sialylation of GFRα1 and facilitating its interaction with RET." (PMID 35582425, 2022). "Conversely, RET missense mutations were more frequently associated with ER+ breast cancers." (PMID 30446652, 2018). "The association reported here between RET SNP rs2435357 and OS in ER+ BC patients is of utmost importance and fully consistent with the observation that RET over-expression is associated with poor prognosis in ER+ BC and strongly candidate this SNP as prognostic factor in ER+ breast cancer." (PMID 27034161, 2016). "However, several recent studies have shown that RET is expressed in a subset of breast cancers and that high RET expression is associated with poor prognosis." (PMID 24466333, 2014). "RET expression is associated with poor outcome in a subset of breast cancers." (PMID 24466333, 2014).